IDH1 (isocitrate dehydrogenase (NADP(+)) 1)
Diseases named in the same sentence as IDH1 in open-access papers (continued):
Sharing a sentence is not in itself a finding about the gene and the disease.
glioma (continued). "The genetic alterations identified in CSF closely mirrored those found in tumor biopsies, including mutations in IDH1/2 and the 1p/19q codeletion, facilitating the development of targeted therapies for glioma." (PMID 40427551, 2025). "Heterozygous missense mutations of arginine to histidine, R132H, make up more than 85% of the genetic alterations in IDH1-mutated gliomas." (PMID 40560010, 2025). "In IDH1/2-mutant gliomas, elevated TERTp mutation rates predominantly reflected oligodendroglioma molecular profiles (with 1p/19q co-deletion), whereas astrocytoma subtypes were characterized by higher ATRX mutation rates." (PMID 41377022, 2025). "For example, among 487 high-grade glioma patients, IDH1 mutation was associated with a 74% reduced VTE risk compared to wild-type (adjusted HR 0.26, 95% CI: 0.08–0.79)." (PMID 39851266, 2025). "In the phase I clinical trial (NCT02193347), the peptide vaccine was tested in patients with grade 2 IDH1 R132H mutation glioma." (PMID 40514725, 2025). "IDH1 R132H mutation led to epigenetic reprogramming of the genome, which resulted in the glioma CpG island methylator phenotype (G-CIMP)." (PMID 40564198, 2025). "IDH1/2 mutations were not only found in gliomas but also in other tumors such as acute myeloid leukemia (AML), myelodysplastic syndrome, myeloproliferative neoplasm, cholangiosarcoma, enchondroma, chondrosarcoma, and other solid cancers." (PMID 40564198, 2025). "When focusing on glioma diagnosis, an ideal testing system requires high diagnostic accuracy by integrating key biomarkers like IDH1 R132, along with DNA sequence alterations and copy number variations." (PMID 40654157, 2025). "IDH1 mutations are predominantly found in lower-grade gliomas and IDH-mutant astrocytomas (Grades II-IV), which were previously referred to as secondary glioblastomas." (PMID 40223032, 2025). "Three probes were designed for the detection of glioma-associated IDH1, colorectal cancer-associated KRAS, and SARS-CoV-2-associated E484A." (PMID 40650970, 2025). "Gliomas harboring isocitrate dehydrogenase 1/2 (IDH1/2) mutations exhibit the CpG island methylator phenotype (CIMP) and are typically associated with improved survival compared to their wild-type counterparts." (PMID 40427130, 2025). "In IDH1/2-mutated tumors such as gliomas, aberrant conversion of α-KG to the oncometabolite 2-hydroxyglutarate consumes NADPH and disrupts the cellular redox balance, increasing the susceptibility of cells to oxidative damage." (PMID 41551149, 2025). "Our study demonstrated a correlation between IDH1 mutation status and glioma grade, with IDH mutations being more common in LGG." (PMID 40944023, 2025). "Whereas IDH1 mutations are more frequent than IDH2 mutations in glioma, the reverse is true for AML." (PMID 40867259, 2025). "IDH-mutant astrocytomas are diffusely infiltrating gliomas defined by mutations in the IDH1 or IDH2 genes." (PMID 40711574, 2025). "Of all glial tumors, 24% (n = 20) and 22.9% (n = 19) carried the IDH1 or IDH2 mutation, respectively." (PMID 39316314, 2025). "We further evaluate the ability of mXO10 tLNP to activate an immune response by delivering glioma-associated antigen IDH1 R132H mRNA to DC cells in the spleen using the SSOCT strategy." (PMID 41381536, 2025). "The recommended technique was evaluated on a brain tumor dataset for IDH1 mutation and IDH1 wild-type gene variation to classify glioma molecular subtypes." (PMID 40520778, 2025). "This redox vulnerability paradoxically correlates with the improved prognosis observed in patients with IDH1-mutant gliomas, likely due to their increased susceptibility to therapy-induced oxidative damage." (PMID 40724998, 2025).
glioma (continued). "A study in glioma patients with IDH1 mutations found 93.3% developed immune responses, with 26/30 showing T-cell and 28/30 B-cell responses, confirming efficacy over 46.9 months median follow-up." (PMID 40443668, 2025). "The preoperative grading of gliomas and the classification of IDH1 mutation status, and the preoperative classification of pituitary tumors are critical to the prognosis of patients and the formulation of surgical plans." (PMID 40127071, 2025). "Glioma tissue (expressing IDH1 R132H/C/G mutations) and cell lines (expressing IDH1 R132H/C/G/S/L mutations) showed varying concentrations of D2HG depending on the IDH1 mutation present, with R132H associated with the lowest levels of D2HG." (PMID 40188944, 2025). "Mutations in IDH1 gene were predictive of longer survival in glioma, which was also reported previously." (PMID 40353995, 2025). "IDH1 R132H, the most frequent IDH1 variant, has been previously associated with increased epileptogenicity and favorable prognosis in lower-grade gliomas." (PMID 40718831, 2025). "The combination of 5hmC biomarkers with IDH1 mutations further enhanced the ability to distinguish glioblastomas from lower-grade gliomas, supporting the value of 5hmC signatures in prognosis stratification." (PMID 40055844, 2025). "Intraoperative prediction of IDH1 mutation status is crucial for evaluating glioma differentiation, predicting biological behavior and prognosis, and optimizing surgical strategy." (PMID 40944023, 2025). "Within the IDH1 mutation cohort, nine cases (18.8%) had high-grade glioma (HGG) lesions, comprising seven cases (14.6%) of glioblastoma, one case (2.1%) of anaplastic astrocytoma, and one case (2.1%) of anaplastic oligodendroglioma." (PMID 40944023, 2025). "Compared with commonly models and new models, our model achieves higher accuracy, with an accuracy of 90.72%, classified glioma IDH1 mutation status with an accuracy of 94.35%, and classified pituitary tumor texture with an accuracy of 94.64%." (PMID 40127071, 2025). "We excluded patients with IDH1-mutant gliomas because IDH1 mutations are associated with favorable survival and are not included in the GBM classification in the 2021 World Health Organization Classification of Tumors of the Central Nervous System." (PMID 40057744, 2025). "Lower-grade gliomas, frequently harboring IDH1 (R132H) mutations, are associated with better prognoses, improved responses to specific therapies, and distinct metabolic and epigenetic profiles." (PMID 39906459, 2025). "In vitro analyses using glioma cell lines engineered to express IDH1 mutations demonstrated elevated levels of ferrochelatase (FECH) and heme oxygenase-1 (HO-1), enzymes involved in heme metabolism." (PMID 41008917, 2025). "The results showed that TERTp mutation is a poor prognostic factor in IDH1/2-wild-type gliomas, but a protective factor in IDH1/2-mutant gliomas." (PMID 41377022, 2025). "Lower-grade gliomas are more likely to have IDH1 (R132H) mutations, which are linked to improved prognosis and greater sensitivity to therapies like radiation and temozolomide." (PMID 39906459, 2025). "MRM-based monitoring further validated the 2-HG/glutamic acid ratio as a predictive biomarker for IDH-1 mutation status in gliomas." (PMID 40863132, 2025). "Gliomas are characterized by a heterogeneous profile of epigenetic dysregulation due to distinct methylation patterns (i.e., IDH1/2 mutations/CpG island methylator phenotype)." (PMID 40091830, 2025). "In fact, children affected by 2HG-acidurias sustained by mutations of IDH1/2 or D/L-2HGDH, exhibit high cancer incidence, particularly of oligodendriomas, low grade gliomas, anaplastic astrocytomas and medulloblastomas." (PMID 39733217, 2025). "The IDHR132H mutation, a common IDH1 mutation in glioma, alters the amino acid arginine for histidine at position 132, found in about 5% of primary GBMs despite its prevalence in low-grade gliomas and secondary GBMs." (PMID 40514725, 2025).
glioma (continued). "Somatic mutations in IDH1 have been implicated in lower grade gliomas, chondrosarcomas, and intrahepatic cholangiocarcinomas." (PMID 40188944, 2025). "Mutations in IDH1 (~80% of grade II-III gliomas and secondary GBMs and ~5% of primary GBMs) and less frequently IDH2 are characteristic of secondary GBM and are associated with a better prognosis." (PMID 39936963, 2025). "Within that study, it was found that mutations in the TERT promoter occurred significantly more often in IDH1 wildtype glioblastomas (187 out of 322; 58%) compared to IDH1-mutated gliomas (10 out of 36; 28%; p = 0.0056)." (PMID 40564017, 2025). "Clinical validation of 95 glioma and 93 colorectal cancer samples showed that IDH1 and KRAS mutations were 100% consistent with Sanger sequencing." (PMID 40650970, 2025). "The most frequent IDH1 mutation in gliomas occurs at codon 132, resulting in an arginine-to-histidine substitution IDH1(R132H)." (PMID 40661781, 2025). "Oligodendroglioma is a central nervous system tumor defined by IDH1/2 mutations and 1p/19q co-deletion." (PMID 40426960, 2025). "The 2021 World Health Organization (WHO) Classification of Tumors of the Central Nervous System (CNS) defines gliomas by their molecular genetic alterations, such as IDH1/2 mutations and 1p/19q co-deletion." (PMID 40994716, 2025). "Of the glioma patients diagnosed and treated at King’s College Hospital, 19.5% had IDH1-mutated tumours and 54.3% were MGMT promoter methylated." (PMID 39767640, 2024). "First, generation of D-2-hydroxyglutarate as a result of the IDH1 mutation has been well studied in gliomas." (PMID 38468344, 2024). "Many gliomas, especially oligodendrogliomas, have mutations in isocitrate dehydrogenase 1 (IDH1) or isocitrate dehydrogenase 2 (IDH2), as well as deletions of chromosome arms 1p and 19q." (PMID 39594997, 2024). "Patients with glioma exhibit a diverse array of genetic mutations, including IDH1 mutation, MGMT promoter methylation, and 1p/19q co-deletion." (PMID 39574472, 2024). "Our study examined the feasibility of using liquid biopsy for patients affected by a brain tumor, and the association between the mutational status of IDH1 in plasma, survival outcomes and clinical characteristics of a cohort of glioma patients." (PMID 38172718, 2024). "We next examined the shift of cell states on the level of individual glioma patients according to IDHstatus, as gliomas with IDH1/2 mutation have been defined as a separate entity, with better prognosis among high grade gliomas." (PMID 38538643, 2024). "With our hiPSC-derived glioma avatar system, we show that glioma-driven mutations, IDH1-mut and EGFRvIII, not only affect the AS landscapes and tumorigenicity, but also modulate the neural differentiation programs." (PMID 38662454, 2024). "It is known that a gain‐of‐function mutation of IDH1/2 genes produces the oncometabolite R‐2‐hydroxyglutarate (R‐2‐HG), which increases DNA and histone methylation contributing to the characteristic glioma‐associated CpG island methylator phenotype (G‐CIMP)." (PMID 38339779, 2024). "Currently, the clinical effectiveness and safety profile of vorasidenib (AG-881), the first dual inhibitor of mIDH1 and mIDH2, in the treatment of glioma with IDH1/IDH2 mutation are being investigated." (PMID 39063158, 2024). "A radiomics model based on DCE-MRI and DWI predicting the IDH1 mutation and angiogenesis in gliomas." (PMID 38672647, 2024). "Reports for patients with gliomas also identified predictive alterations in IDH1 (19.0%) or BRAF (V600E mutation 3.4%, fusion 2.8%)." (PMID 37682776, 2024). "IDH1 gene mutations are implicated in various malignancies, including gliomas, leukaemia, and cholangiocarcinoma." (PMID 38398089, 2024).
glioma (continued). "On the other hand, IDH-mutant gliomas are characterized by a class-defining and possibly tumor-initiating clonal IDH1 or IDH2 gene mutation." (PMID 38539436, 2024). "first described six patients with RRD HGG with secondary IDH1 mutations that clustered with other IDH1 mutant gliomas on methylation profiling." (PMID 39876890, 2024). "In this subgroup analysis, even patients with IDH1/2 mutation (Group B), previously known as a better prognostic factor for glioma, had shorter PFS and OS than patients with the IDH1/2 wildtype if accompanied by CDKN2A deletion (Group C)." (PMID 39457569, 2024). "The present study evaluates the ability of liquid biopsy to detect IDH1 mutations and its correlation with survival and clinical characteristics of glioma patients." (PMID 38172718, 2024). "IDH1 mutations impact the immune landscape of gliomas by affecting immune infiltrations and manipulating checkpoint ligand PD‐L1 expression." (PMID 38733169, 2024). "In gliomas harboring pathogenic IDH1 mutations, the activation of the PI3K/AKT pathway is implicated in tumor progression and treatment response." (PMID 38562143, 2024). "Loss of ATRX expression, often coupled with IDH1 mutations, is common in gliomas and is associated with specific subtypes such as astrocytomas." (PMID 39459454, 2024). "A phase II study assessed the efficacy and safety of DS-1001b in patients with chemotherapy- and radiotherapy-naive IDH1-mutated WHO grade 2 gliomas." (PMID 39123479, 2024). "For this reason, we focused not only on the group comparisons between (i) LGG vs. HGG but also investigated the differences between (ii) IDH1/2 wildtype vs. IDH1/2 mutated gliomas and (iii) high-grade oligodendroglial vs. high-grade astrocytic gliomas." (PMID 39123372, 2024). "Oligodendrogliomas are infiltrating gliomas that, by definition, possess mutations in the IDH1 or IDH2 genes and whole arm co-deletion of chromosomes 1p and 19q." (PMID 39707480, 2024). "One-way ANOVA revealed that low-grade glioma, gross total resection, the presence of an IDH1 mutation, and tumors located in the frontal or temporal lobes were protective factors." (PMID 38982076, 2024). "Our study showed that younger patients are more likely to be diagnosed with an IDH1-mutated glioma than with a wild-type form and that this mutation is rarely found in the elderly patient population." (PMID 39767640, 2024). "IDH1: IDH1 mutation correlates with better overall outcome, and high-grade gliomas with proven IDH1 mutation are now reclassified according to the new WHO classification as astrocytomas grade 4." (PMID 38674026, 2024). "IDH1 mutations occur mainly in the early stage of tumors, especially in gliomas and glioblastoma multiforme." (PMID 39512821, 2024). "IDH1 mutation in brain lower grade glioma associates with lower lymphangiogenesis and metastasis possibly by down regulating PDPN gene expression." (PMID 38241355, 2024). "In line with prior research, our study highlighted the prevalence of IDH1 mutation in younger glioma patients, which also correlated with improved overall survival." (PMID 39348350, 2024). "Patients with hypermethylated MGMT and the IDH1 p.R132H mutation had a better prognosis for their glioma." (PMID 39132504, 2024). "One study found that VASARI features, including the proportion of necrosis and lesion size, were associated with IDH1 mutation status in gliomas." (PMID 39100020, 2024). "Patients with high-grade gliomas carrying IDH1 or IDH2 mutations are also usually younger than those with IDH1/IDH2-wild-type glioma." (PMID 38891962, 2024). "Mutations in the IDH1 gene occur in codon R132, with >90% of mutations in gliomas associated with arginine to histidine (p.R132H) substitution, while a wider range of amino acid changes have been observed in chondroid tumors." (PMID 38248076, 2024).
glioma (continued). "In the present study, we assessed the feasibility of detecting plasma-cfDNA IDH1 mutation in gliomas and the results were correlated with survival and clinical characteristics of patients affected by gliomas." (PMID 38172718, 2024). "Lastly, we compared glioma samples based on the mutation status of isocitrate dehydrogenase 1 (IDH1), a well-established molecular marker of glioma that indicates lower-risk disease." (PMID 38971800, 2024). "Isocitrate dehydrogenase 1 (IDH1) is also associated with seizure risk, and patients with IDH1 mutations in low-grade gliomas have a perioperative seizure risk high." (PMID 38574171, 2024). "Studies of Safusidenib in patients with IDH1-mutated WHO glioma are ongoing (NCT04458272, NCT05303519 and NCT05577416)." (PMID 39876890, 2024). "In one study based in India, Indian patients with glioma were revealed as more likely to be diagnosed with a low-grade glioma and to have a higher prevalence of IDH1 mutation, giving them an improved outcome." (PMID 39767640, 2024). "This systematic approach proved that IDH1 mutation is attributed to decreased chemotaxis in IDH‐mutant gliomas leading to decreased immune cell infiltration." (PMID 38339779, 2024). "Given the distinct characteristics of IDH1 mutant and IDH1 wild-type tumors, Beiko and colleagues examined the impact of IDH1 mutation on the surgical resection and survival outcomes of patients with glioma." (PMID 39123366, 2024). "Prior clinic research demonstrated that isocitrate dehydrogenase 1 (IDH1) mutation altered phospholipid metabolism and resulted in decreased PE level in glioma." (PMID 39021629, 2024). "Peptides including the mutated region were presented with MHC class II molecules and elicited a mutated specific CD4+ (TH1) immune response in mice models with IDH1 mutated gliomas, making it a possible neo-antigen for IDH1 mutated AMLs." (PMID 39770471, 2024). "Recent work has shown that mutant IDH1 cooperates with ATRX loss in promoting the alternative lengthening of telomere (ALT) phenotype in gliomas, highlighting mechanisms of pathogenic interplay between the two molecular abnormalities." (PMID 38272925, 2024). "IDH1 is frequently mutated in multiple cancers, especially in low grade glioma and acute myeloid leukemia." (PMID 38965614, 2024). "Apart from solid malignancies which typically harbor IDH1/2 mutations as leading driver mutations (gliomas, iCCAs, chondrosarcoma, and SNUCs), many other solid tumors develop IDH mutations as a late event during disease progression." (PMID 39123479, 2024). "Diffuse gliomas are primarily classified along their isocitrate dehydrogenase (IDH1/2) mutation and 1p/19q codeletion status." (PMID 38791871, 2024). "IDH1 wild-type gliomas had higher neurotransmitter levels, possibly linked to their poorer prognosis." (PMID 39227460, 2024). "IDH1 is one of the key enzymes of tricarboxylic acid cycle, and its coding gene mutation has a high frequency in gliomas, with glioma specificity." (PMID 38734702, 2024). "Mutations in IDH1/2 significantly change the epigenome contributing to blockade of cell differentiation and glioma development." (PMID 38711090, 2024). "Despite the excellent overall diagnostic performance of algorithmic approaches, it appears that balancing methods are underutilized, resulting in worse performance for smaller tumor subgroups (e.g., 1p/19q codeleted or IDH1/2 mutated gliomas)." (PMID 38791871, 2024). "A previous study had demonstrated the clinical potential of DCE-MRI in the evolution of glioma IDH-1 mutation." (PMID 39285364, 2024).